ATF6 (activating transcription factor 6)
Diseases named in the same sentence as ATF6 in open-access papers (continued):
Sharing a sentence is not in itself a finding about the gene and the disease.
cancer (continued). "Accordingly, the sustained activation of the ATF6 pathway also strengthens vascular neogenesis and improves the immunogenicity of cancer cells." (PMID 39319052, 2024). "Knockdown of ATF6α induces apoptosis in dormant cancer cells, prolonging the period of cell dormancy and delaying the onset of recurrent cancer cell growth." (PMID 38509524, 2024). "Our report marks an important advance in establishing ATF6 as a compelling novel target for the treatment of cancer." (PMID 39324706, 2024). "Malignant cells can co-opt IRE1 and PERK to sustain growth; however, the importance of ATF6 in cancer remains poorly deciphered." (PMID 39324706, 2024). "ATF6 plays a crucial role in cancer development and has been found to regulate carcinoma progression through mTOR or PERK signaling pathways." (PMID 38672148, 2024). "ATF6 plays a vital role in a variety of cancers; e.g., by regulating cell growth, migration, apoptosis, and autophagy in cervical cancer." (PMID 37456776, 2023). "AGR2 has been demonstrated to be upregulated upon ER stress, and ER stress-related molecules, such as PERK, IRE1 and ATF6, are dysregulated in many cancer types." (PMID 36899352, 2023). "The inhibition of all three UPR sensors, PERK, IRE1 alpha (henceforth, IRE1), and ATF6 limits cancer angiogenesis." (PMID 36408145, 2022). "The ERS, mediated by three conservative pathways: IRE1a‐XBP‐1, PERK‐eIF2a, and ATF6, plays a key role in cancer development." (PMID 35390056, 2022). "To further demonstrate the role of ATF6 in protecting stressed cancer cells from cell death, preventing DNA damage, and sustaining the expression of BRCA-1, we silenced ATF6 prior exposing cells to DPE or Thapsigargin." (PMID 35752616, 2022). "Previous reports indicated that the ATF6 fragments enhance nuclear translocation in multiple cancers, including HCC and Hodgkin’s lymphoma." (PMID 36497032, 2022). "The oncogenic UPR signal pathways were reported to include PERK, IRE1α, and ATF6 pathways and perhaps helps cancer cells to overcome oncogenic stress." (PMID 35205628, 2022). "Several other genes, such as BCAT1, BCL2, and ATF6, are related to prognosis in other types of cancers." (PMID 34771630, 2021). "Many GPCRs modulate ERS and UPR signaling via ERS sensors, IRE1α, PERK, and ATF6, to support cancer cell survival and inhibit cell death." (PMID 33746610, 2021). "By shifting S1P and S2P to ATF6 and simplifying the ER stress pathway, cancer cells can rapidly provide an appropriate level of UPR to compensate for the need for AR protein itself and subsequent AR-triggered proliferation." (PMID 34521429, 2021). "Of note, the ATF6-dependent UPR exerts cyto-protective effects to accelerate cancer progression and drug resistance." (PMID 34381729, 2021). "As observed in other cancers, our study indicated that of ATF6 increased expression correlates with poor prognosis of PC." (PMID 35222510, 2021). "Higher expression level of ATF6 has been closely correlated with cancer metastasis and recurrence and served as a prognostic indicator of cancer." (PMID 33267910, 2020). "Due to the major pro-survival role of ATF6, its expression level has been shown to be significantly upregulated in various cancer types." (PMID 33267910, 2020). "ATF6 promotes Xbp-1 and GP96 expression, and ATF6 expression correlates with poor prognosis in a number of cancers." (PMID 30978945, 2019). "In parallel, ATF6 inhibitors are employed against cancer, for instance Nelfinavir, firstly identified as viral proteases inhibitor, was then shown as S1P/S2P proteases inhibitor together with its derivate." (PMID 31671908, 2019). "Due to the general pro-survival role of ATF6, its significantly increased level has been widely shown to occur in various cancer types." (PMID 31491919, 2019).
cancer (continued). "Compounds interacting directly with UPR mediators (e.g., PERK, IRE1a or ATF6) can also be valuable therapeutic agents for the treatment of neurodegeneration and cancers." (PMID 31671908, 2019). "In a CRC model, the activation of XBP1 and ATF6 resulted in reduction of stemness and proliferation of cancer cells via the crossactivation of the PERK-eIF2α signaling pathway." (PMID 31491919, 2019). "With relevance to cardiac disease, cancer and brain disorders, the importance of ATF6 in maintaining tissue homeostasis is the subject of the final section." (PMID 29801500, 2018). "Consistently, several in vitro and in vivo experiments suggest that ER molecular chaperons induced by active ATF6α play critical roles in cancer progression." (PMID 30504895, 2018). "Activating transcription factor 6 (ATF6), one of the three major ER stress transducers, has been shown to contribute to chemoresistance by altering cancer cell survival." (PMID 30063110, 2018). "Cumulative evidence has indicated that ER stress, especially GRP78, which is a downstream target of ATF6, was correlated with chemotherapy resistance in cancer cells." (PMID 30063110, 2018). "P38 phosphorylation contributes to the nuclear translocation and activation of ATF6α in dormant cancer cells through the ATF6α/Rheb/mTOR pathway." (PMID 30134550, 2018). "The UPR-related proteins GRP78and ATF6 are highly expressed in cancer cells and are involved in promoting cancer cell proliferation and survival under extreme conditions." (PMID 27638465, 2017). "Through pro-survival signaling mediated by ATF6, activation of the ER stress response has been shown to contribute to enhanced viability in several cancers." (PMID 26716508, 2016). "Mechanistically, rutin was reported to considerably reduce ROS, IRE1, PERK and ATF6 to induce apoptosis in cancer cells." (PMID 25493075, 2014). "The properties related to cancer verified that, if S1P/S2P in the Golgi apparatus is continuously activated, it will continuously process ATF6 and activate the synthesis of the oncoproteins XBP1 and cMYC." (PMID 25522186, 2014). "To determine if PRNP gene expression in the basal carcinoma cell lines depends on ER stress, we knocked down (KD) ATF6α and XBP1 with siRNAs in the MDA-MB-231 and HS578T cell lines." (PMID 23497519, 2013). "Interestingly, it has been recently demonstrated in cancer cells that ATF6α can prevent DNA damage in response to the cytotoxic effects of ER stressors." (PMID 40241256, 2025). "Additionally, ATF6’s interactions with its chaperone proteins are essential for cancer cell survival." (PMID 41301006, 2025). "Importantly, disease-free survival was significantly reduced in cases of combined ATF6 and FASN amp/gain compared to those showing ATF6-only amp/gain in the Pan-Cancer Atlas (P = 0.0394), with a trend observed in the TCGA database (P = 0.4046)." (PMID 40890536, 2025). "PERK, IRE1α and ATF6 are crucial for the adaptation of cancer cells to their changing environment." (PMID 40873119, 2025). "Aberrant regulation of unfolded protein response (UPR)/endoplasmic reticulum (ER) stress pathway is associated with cancer development, metastasis, and relapse, and the UPR signal transducer ATF6 has been proposed as a diagnostic and prognostic marker for many cancers." (PMID 39401430, 2024). "Additionally, ATF6 has been found to play a significant role in the tumor microenvironment, promoting the growth of cancer cells and the development of metastases." (PMID 38672148, 2024). "In addition, studies have shown that GPCRs modulate UPR signaling via ERS sensors, IRE1α, PERK, and ATF6, to support cancer cell survival and inhibit cell death." (PMID 38700505, 2024). "Indeed, great multi‐cancer diagnostic value in tissues was observed in small eccDNAs originated from some specific genes, especially the combination of PLD1 and ATF6, or ETV6 and ALK." (PMID 37649244, 2023).
cancer (continued). "ATF6-associated autophagy participates in ovarian cancer cell chemoresistance, death-associated protein kinase 1 (DAPK1)-related chronic lymphocytic leukemia cell death, and cancer-associated fibroblast (CAF) activation in lung adenocarcinoma progression." (PMID 37456776, 2023). "ATF6 serves as an important regulator of organogenesis and tissue homeostasis, and aberrant ATF6 activity may promote the pathogenesis of various cancers." (PMID 37649244, 2023). "Further studies are required to reveal the exact mechanism of ATF6 in cancer." (PMID 35222510, 2021). "The function of ATF6 in cancer progression seems contradictory." (PMID 34073612, 2021). "Expression of ATF6 mRNA and protein levels is detected in cancer cell lines and tumor samples." (PMID 33746610, 2021). "The UPR, which is mediated by activating transcription factor 6 α (ATF6α), inositol requiring enzyme 1 alpha (IRE1α), and protein kinase R-like endoplasmic reticulum kinase (PERK), has been implicated in chemoresistance and cancer development." (PMID 32630838, 2020). "We further identified that STAT3 functions to promote the transcription of the activating transcription factor 6 (ATF6), which induces endoplasmic reticulum stress to promote cellular autophagy, granting cancer cell resistance to both cisplatin and paclitaxel treatment." (PMID 32080166, 2020). "The study suggests that Ceapin may be used for the treatment of cancer, since cancer development relies on active ATF6α signaling; this finding presents a novel drug-development strategy for targeting the MCS." (PMID 32714927, 2020). "Thus, we have uncovered a mechanism in which ID1 confers cancer cell chemoresistance largely through the STAT3/ATF6-induced autophagy." (PMID 32080166, 2020). "Therefore, ceapins, a class of pyrazole amides are a promising group of small molecules targeting ATF6α to inhibit cancer cell proliferation." (PMID 31121863, 2019). "Interestingly, a high level of ATF6 has been strictly correlated with cancer metastasis and recurrence." (PMID 31491919, 2019). "ERSR or UPR is initiated in cancer cells, through three ER sensors ATF6, IRE1, and PERK." (PMID 30857233, 2019). "Moreover, high expression of ATF6 has been found in recurrent tumors and to be correlated with increased chemoresistance, suggesting a functional link between ATF6 and cancer cell dormancy and subsequent resistance to treatment." (PMID 31739582, 2019). "Further, ATF6 has been known to be involved in the regulation of cancer cell dormancy." (PMID 31739582, 2019). "Some of the transcription factors that were specifically expressed in OS-DW cells were ATF6, CDX2, FOSL1, PRDX3, FZD6, MYNN, TRAF1 which are known to regulate pathways implicated in cancers like, Wnt/Hedgehog/Notch signaling, MAPK signaling, Apoptosis and mTOR signaling." (PMID 31690262, 2019). "ATF6 is reported to also be activated in several types of cancer." (PMID 28884228, 2018). "Consistent with this hypothesis, previous results have shown that PDIA5 has a critical role in regulating ER stress-dependent ATF6 activation in cancer cells." (PMID 30084354, 2018). "To analyze whether HRD1-dependent ATF6α activation could mediate the role of TUSC3 in cancer metastasis, we performed a series of rescue experiments." (PMID 30504895, 2018). "Through activating UPR, ATF6 may play an important role in promoting survival of dormant cancer cells via stimulating the mTOR pathway." (PMID 28884228, 2018). "In summary, our studies demonstrated that berberine could induce GRP78 expression by activation of ATF6 cleavage, and inhibition of ubiquitination and proteasomal degradation, further resulting in autophagy and cancer cell death." (PMID 28157699, 2017). "Activation of ATF6α promotes cell survival in cancer models." (PMID 27435960, 2016).
cancer (continued). "In contrast with these data, ricin and the RIP riproximin were recently reported to inhibit eIF2-α phosphorylation and to decrease intact ATF-6 protein in two human cancer cell lines, MCF-7 and HCT-11, indicating that these two UPR pathways were induced by toxin treatment." (PMID 22069719, 2011). "Thus, inhibiting IRE1α, PERK, and ATF6α is a promising novel therapeutic modality for cancer treatment." (PMID 20221394, 2010). "The relationship between ATF6-high and FASN-high individuals is evident through their association classified as co-occurrence, despite not reaching significance in the TCGA database (P = 0.297), likely due to lower case numbers compared to the Pan-Cancer Atlas database (P < 0.001)." (PMID 40890536, 2025). "Thus, ATF6 mediates autophagy via LC3B upregulation for cancer cell survival, but ATF6 down-regulation could reverse dormant cell resistance in vivo." (PMID 36497032, 2022). "Redox-mediated activation of IRE1α and ATF6α may support dormant cancer cell survival, while activating PERK phosphorylates eukaryotic initiation factor 2α (eIF2α) and inhibiting its translation of cyclin-dependent kinases (CDK4), Cyclin D1/D3, leading to quiescence of dormant cancer cells." (PMID 34685686, 2021). "Besides, the activation of ATF6α is crucial for cancer cell survival." (PMID 31121863, 2019). "Compared to IRE1 and PERK, ATF6 in cancer is largely unknown." (PMID 31739582, 2019). "Taken together, we found that HDACi synergize with Gem in eliciting ER-stress and activating all three major UPR branches in PDAC cancer cells, with a preference for the PERK/ATF4 and IRE1/XBP1 arms and with a weaker activation of the ATF6 arm." (PMID 40287668, 2025). "Cancer cells can exploit UPR to promote proliferation and metastasis, mainly via the downstream transcriptional factors XBP1s, ATF4, and cleaved ATF6." (PMID 41193471, 2025). "To investigate the impact of each arm of the UPR in driving the observed cancer-specific effects of DT-061, we examined protein expression patterns of PERK, IRE1α, ATF6, and their downstream targets." (PMID 39349971, 2024). "Small molecule inhibitors of IRE1, PERK and ATF6 are available with several, particularly those targeting IRE1, showing a significant therapeutic benefit in preclinical models of cancer." (PMID 38637497, 2024). "In high-grade serous ovarian cancer, ATF6 is activated by STAT3 and in turn induces the UPR to promote autophagy, thereby leading to cancer cell resistance to both cisplatin and paclitaxel treatment." (PMID 38297380, 2024). "For instance, PERK inhibitors like GSK260641 and ATF6 (exemplified by 16F16), along with the CHOP inducer (like DK143), present promising avenues for intervention in cancer treatment." (PMID 39448589, 2024). "In vivo and in vitro validation confirmed that overexpressed NUCB1 protein inhibits cell proliferation and by ATF6 regulation, NUCB1 increases drug sensitivity of cancer cells." (PMID 36611989, 2023). "CAL 27 and Ca9-22 cancer cells showed a higher mRNA expression of BIP, IRE1α, and ATF6 genes than the untreated control, particularly at 10 μM manoalide, but these were slightly changed in normal cells." (PMID 36835397, 2023). "Depletion of ALKBH5 increased the levels of the UPR sensor proteins PERK, ATF4, ATF6, and IRE-α in normal and cancer cell lines." (PMID 37174684, 2023). "In cancers, OTUB1 was proved to promote cancer progression via stabilizing ATF6 protein and PDL1 for cancer cell immune evasion." (PMID 36271031, 2022). "Accordingly, ATF6 silencing induced a stronger DNA damage in terms of γH2AX expression level and further downregulated BRCA-1 in cancer cells stressed by DPE or Thapsigargin." (PMID 35752616, 2022). "IRE1α, PERK, and ATF6 are three well-known sensors that activate UPR, controlling the balance between cell survival and apoptosis during ER stress in cancer." (PMID 35326553, 2022).
cancer (continued). "H6PD was found to promote cancer cell proliferation and the modulation of its expression affected GRP78, ATF6 and CHOP, emphasizing its role in ERS regulation." (PMID 35030165, 2022). "ATF6, XBP1, and CHOP were identified as core proteins in UPR signaling, which contribute to various physiological processes and cancer development." (PMID 35222510, 2021). "PERK, ATF6, and IRE1 are considered core components in UPR signaling and are important for cancer progression." (PMID 32034256, 2020). "(A) mRNA-expression of ER-stress markers ATF6, ATF4, EIF2AK3, GADD34, EDEM1, DDIT3 and HSPA5, in stellate cells (LX2) co-cultured with cancer cells (HepG2 or Huh7) and treated with 4μ8C or control." (PMID 33103995, 2020). "When the folding capacity of the ER is exceeded, cancer cells trigger the UPR activating PERK, IRE1 and/or ATF6-dependent signalling pathways as shown in different types of cancer." (PMID 31071975, 2019). "In melanoma, both ATF6 and PERK branches of the UPR are involved in the induction of the fibroblast growth factors FGF1/2 increasing cancer cell migration in vitro." (PMID 31064137, 2019). "The inositol-requiring enzyme 1 alpha (IRE1), activating transcription factor 6 alpha (ATF6), and glucose-regulated protein 78 (GRP78), play a critical role in chemotherapy resistance in cancers." (PMID 30857233, 2019). "We found that NDV infection activated all three branches of the UPR signaling (PERK-eIF2α, ATF6, and IRE1α) and triggered apoptosis, in avian cells (DF-1 and CEF) and in various human cancer cell types (HeLa, Cal27, HN13, A549, H1299, Huh7, and HepG2)." (PMID 31767828, 2019). "Previous studies have shown that ER stress-activated genes mediated by the unfolded protein response (UPR, PERK, ATF6, and IRE1) are involved in autophagy or apoptosis in several cancers." (PMID 28212571, 2017). "Gene silencing strategy also confirmed that PERK, ATF6 and IRE1 silenced cancer cells displayed a higher apoptotic rate." (PMID 25493075, 2014). "The accumulation of misfolded proteins in the ER is cytotoxic, prompting cancer cells to activate UPR pathways mediated by inositol-requiring enzyme 1a (IRE1a), activating transcription factor 6 (ATF6), and protein kinase RNA-like endoplasmic reticulum kinase (PERK) to mitigate ER stress." (PMID 41343245, 2026). "While the study concentrated on the gene expression of four pivotal proteins (IRE1, PERK, ATF6, and CHOP), investigating additional molecular pathways may yield a more holistic understanding of the interplay between stress responses and cancer growth." (PMID 39813534, 2025). "At the same time, the increased production of ROS may directly promote the up-regulation of ERS-related proteins (ATF6, GRP78, XBP1s), which play an anti-cancer role as a medium." (PMID 39319052, 2024). "In tumors, cancer cells are prone to many stresses which can disturb protein synthesis and folding accuracy and overwhelm protein quality control processes thus leading to ER stress and activation of the PERK, ATF6 and IRE1-XBP1s UPR signaling pathways." (PMID 38909090, 2024). "Moreover, in three cancer cell lines (A549, MGC-803, and SW480), we analyzed the expression changes of PERK and ATF6 following RPN1 knockdown." (PMID 39749324, 2024). "Over the past 30 years, significant advances have been made in understanding IRE1, PERK and ATF6 dependent pathways, how they co-ordinate the UPR to aid ER stress resolution, and when dysregulated contribute to the progression of diseases such as cancer." (PMID 38637497, 2024). "PERK, IRE1α, and ATF6 are critical mediators of the unfolded protein response (UPR) in endoplasmic reticulum (ER) stress, influencing cancer progression, survival, and therapy resistance by modulating cellular responses ranging from adaptive survival to apoptosis." (PMID 38256073, 2024). "Although there are no FDA-approved regimens for targeting ATF6 in cancers, three reported ATF6 inhibitors with different modes of action have shown great efficacy." (PMID 37704840, 2023).